GCG (glucagon)
Diseases named in the same sentence as GCG in open-access papers (continued):
Sharing a sentence is not in itself a finding about the gene and the disease.
Hyperglycemia (continued). "In fact, the elevated glucagon levels could have also contributed to the development of hyperglycemia as it is known that glucagon stimulates glucose production from the liver." (PMID 22586489, 2012). "Here we sought to determined a possible functional parallel between the enlargement of islet size in response to taurine supplementation, the number of islets, the resistance to glucose-induced hyperglycemia and the levels of the three main pancreatic peptides: insulin, glucagon and somatostatin." (PMID 20804628, 2010). "Hyperglycaemia in critical illness is believed to reflect inadequate insulin secretion, hepatic and peripheral insulin resistance, and an increase in the counter-regulatory hormones cortisol, catecholamines, glucagon and growth hormone." (PMID 19439067, 2009). "Exenatide (ByettaTM), the first such compound to be licensed by the European Medicine Agency (EMEA), enhances glucose-dependent insulin secretion, regulates glucagon release, and delays gastric emptying thereby reducing hyperglycaemia in a similar manner to GLP-1." (PMID 18694484, 2008). "Interestingly, this period is characterized by physiological hyperglycemia and hyperinsulinemia, where peripheral insulin resistance and a high plasmatic concentration of glucagon are also observed." (PMID 17183663, 2006). "However, this same unopposed glucagon effect can also contribute to delayed postprandial hyperglycemia, particularly after larger protein loads or mixed meals, due to increased hepatic gluconeogenesis occurring in the absence of dynamic insulin secretion/delivery." (PMID 41602572, 2026). "Indeed, we observed impaired beta cell mass and insulin labeling with an increased proportion of glucagon-positive cells per islet, which could further contribute to overall hyperglycemia." (PMID 41017587, 2025). "In addition, excessive glucagon secretion may contribute to hyperglycemia, as elevated postprandial glucagon concentrations have been observed in T1DM patients." (PMID 39996055, 2025). "Furthermore, glucagon-induced amino acid catabolism may contribute to muscle wasting, supplying substrates for gluconeogenesis and thereby perpetuating hyperglycemia." (PMID 40822953, 2025). "Hence, one mechanism of hyperglycemia during morphine or opium withdrawal syndrome is that stress-induced hypercortisolism may affect the pancreas, motivating glucagon release and thus leading to hepatic glucose production." (PMID 40290115, 2025). "Moreover, reduced insulin levels may lead to increased glucagon secretion, further aggravating hyperglycemia through enhanced hepatic glucose output." (PMID 41465559, 2025). "Likewise, diminishing alpha-cell glucagon secretion via D2R agonism may concurrently lower hyperglycemia and improve both insulin resistance and overall glycemic control." (PMID 39906261, 2025). "Therefore, both insulin deficiency and a lack of suppression of glucagon in the post-oral glucose challenge concur with hyperglycemia." (PMID 39519472, 2024). "Therefore, insulin insensitivity or elevated glucagon can be ruled out as a cause of hyperglycaemia upon B7-H4 knockout in β cells." (PMID 39571901, 2024). "High glucagon may, via systemic hyperglycaemia, increase glucose availability in the brain." (PMID 38977507, 2024). "We hypothesize that gedatolisib may not affect pancreatic islet cells, hepatocyte potency, or drug uptake sufficiently to trigger glucagon release, glycogenolysis, and gluconeogenesis that would, in turn, lead to sustained systemic hyperglycemia and/or hyperinsulinemia." (PMID 38839777, 2024). "Consequently, abnormalities in glucagon physiology may contribute to the development of fasting and postprandial hyperglycemia in the pathogenesis of type 1 diabetes (T1D) and its therapy." (PMID 39149119, 2024).
Hyperglycemia (continued). "Due to the β-cell-intrinsic role of TALK-1 L114P channels, the effect of somatostatin on glucose-stimulated insulin secretion might be limited; however, it remains to be determined if the fasting hyperglycemia observed in KCNK16-MODY patients is due in part to elevated glucagon secretion." (PMID 38700926, 2024). "Furthermore, a recent study demonstrated that the elevation of serum ALT levels was linked to hyperglycemia in T2DM patients and that silencing both ALT isoforms could retard hyperglycemia in T2DM mouse models via chronic glucocorticoid and glucagon signaling." (PMID 38232082, 2024). "Moreover, GS increase glucagon secretion from alfa cells, which leads to hyperglycemia." (PMID 39407860, 2024). "It has been hypothesized that the initial lack of glucagon suppression or hypersecretion during a high-carbohydrate meal indicates that the cellular response to hyperglycemia is diminished, although the exact mechanism underlying this impact is still unclear." (PMID 37628857, 2023). "Thus, HFD consumption in low-5HT animals resulted in hyperglycemia and hyperinsulinemia, glucose intolerance and insulin resistance, as well as elevated blood leptin, cholesterol and triglycerides (TG) levels, and decreased glucagon levels." (PMID 36768493, 2023). "This glucagon–insulin imbalance could explain the occurrence of hyperglycemia." (PMID 37628857, 2023). "In addition, elevated fasting and postprandial plasma glucagon concentrations have also been shown and may contribute to symptomatic hyperglycemia." (PMID 37008952, 2023). "Some authors propose that loss of beta cell GIPR function due to cell stress in T2DM patients may reduce the inhibitory effect of insulin on glucagon secretion, leading to elevated GIP-stimulated glucagon secretion even during hyperglycemia, but this hypothesis is controversial." (PMID 37635984, 2023). "Hyperglycemia observed after glucose load in type 2 diabetic humans normally results from both insulin resistance and impaired β-cell function, which is similar to our study where the insulin level is also increased along with glucagon and glucose in the PC group." (PMID 35078449, 2022). "In female mice, hyperglycemia (>10 mM) resulted in mildly elevated insulin secretion in βInsrKO relative to control mice for the initial 48 h, which was not sustained for the duration of the experiment, while glucagon levels declined similarly in both genotypes." (PMID 35136059, 2022). "The contribution to the hyperglycemia attributable to glucagon‐induced increases in hepatic glucose output may be mediated by GR1 activation alone or by the activation of both GR1 an GR2 receptors, depending at least in part on the magnitude of the increase in plasma glucagon concentrations." (PMID 35569125, 2022). "Several studies have found that fasting hyperglucagonemia is associated with fasting hyperglycemia through increased hepatic glucose production, but the higher glucagon concentration in the CRHP group was not accompanied by a concomitant increase in basal glucose concentration in the present study." (PMID 36061897, 2022). "When exploring the data from the individual mice, we found that the long-term hyperglycemia, calculated as the AUC of the glucose curves during the 8-week study, negatively correlated to the percentage of insulin+ cells and positively correlated with the percentage of glucagon+ cells." (PMID 35203411, 2022). "Insulin is also required, in the first instance, for treatment of SIH, as reported in NICE recommendations, but it is frequently not enough to control acute hyperglycaemia because it is not able to suppress glucagon secretion, which is one the principal causes of SIH." (PMID 33466656, 2021).
Hyperglycemia (continued). "Regulation of glucagon secretion is impaired in subjects with T2DM who have elevated plasma glucagon concentrations in the fasting state and defective postprandial glucagon suppression that results in undesirably high plasma glucagon concentrations in the context of hyperglycemia." (PMID 33758717, 2021). "In addition, concurrent with reduced insulin secretion, an imbalance in the insulin-glucagon axis during hyperglycemia with a reduced glucose-induced glucagon suppression has been described in a study that included Caucasian kidney transplant patients with PTDM." (PMID 34198724, 2021). "It turns out that the mitochondrial dysfunction causes an increased glucagon secretion in hyperglycemia, whereas glucagon secretion decreases in the hypoglycemic region, as the ATP production is not sufficient to fulfil the conditions for elevated glucagon secretion." (PMID 33327428, 2020). "We believe that recent data suggests that glucagon elevation is an adaptive reaction as opposed to an early causative step in hyperglycemia, similar to the accepted view that the hyperinsulinemia induced by insulin resistance is an adaptive function of β-cells." (PMID 32964214, 2020). "Importantly, GLP-1 ameliorates the hyperglycaemia which is provoked by glucagon." (PMID 32436022, 2020). "However, glucagon has the undesired effect of provoking hyperglycaemia." (PMID 32436022, 2020). "Thus, elevated glucagon in human T2D may reflect α-cell insensitivity to paracrine inhibition at hyperglycemia." (PMID 32312960, 2020). "Moreover, given the integral role for glucagon action in olanzapine-mediated hyperglycemia, estrogen mediated reductions in glucagon secretion could similarly attenuate glycemic dysregulation post-acute olanzapine." (PMID 31555747, 2019). "In addition, alterations in meal patterns, fluid intake, circadian rhythms and the sleep–wake cycle can disrupt the normal physiology of counter‐regulatory hormones (such as glucagon, cortisol and catecholamines), and therefore, increase the likelihood of hyperglycemia and diabetic ketoacidosis." (PMID 30938074, 2019). "In addition, despite the lack of hyperglycaemia induced by the co‐agonist, the glucagon‐associated effects of increased energy expenditure and improved lipid profile were preserved." (PMID 30466162, 2019). "The finding that glucose also remains capable of inhibiting glucagon secretion in depolarized islets raises the interesting possibility that hyperglycemia may also inhibit glucagon secretion by a P/Q‐type channel‐dependent process, independent of membrane potential." (PMID 30187652, 2018). "The most frequent anti-diabetic drugs are focused in preventing and reducing hyperglycaemia, and include drugs able to inhibit carbohydrate absorption, endogenous glucose production, insulin sensitizers, insulin secretagogues, insulin receptor agonists, and inhibitors of glucagon release." (PMID 28042834, 2016). "Although the mechanism of hyperglycemia induced by scorpions’ venom is not clearly understood, there are studies demonstrating that it can occur through the excessive release of catecholamine, increases in glucagon and cortisol, and alterations in thyroid hormone levels or insulin secretion." (PMID 27660634, 2016). "Together, these findings indicate that although glucagon signaling blockade does not prevent hyperglycemia in diabetic mice that exhibit extreme insulin deficiency, it results in enhanced formation of new insulin-producing cells by increasing the absolute number of converting α-cells." (PMID 27092792, 2016). "The importance and clinical consequence of alpha cell hyperplasia are largely unknown due to lack of data, but it is not impossible that, after stopping liraglutide, the previous suppressed glucagon secretion could rebound, resulting in relapse of hyperglycemia." (PMID 26640805, 2016). "Additionally, disruption of glucagon activity was shown to improve hyperglycemia in ob/ob mice." (PMID 26075596, 2015).
Hyperglycemia (continued). "This study indicates in patients with critical illness-associated hyperglycaemia that acute intravenous administration of GIP at pharmacological doses has no insulinotropic activity, does not reduce elevated blood glucose concentrations but does cause a significant postprandial rise in glucagon." (PMID 25613747, 2015). "There is no curative treatment for T2DM; all available therapies attempt to control hyperglycemia by attenuating one or more of the pathophysiological pathways—reducing insulin resistance and thereby increasing glucose processing and/or curtailing excessive glucose release through glucagon action." (PMID 24918743, 2014). "Furthermore, mice lacking α-cell specific insulin receptor exhibited elevated glucagon secretion, hyperglucagonemia in the fed state, impaired glucose intolerance and hyperglycemia, indicating the inhibitory effects of intra-islet insulin on glucagon secretion." (PMID 23316165, 2012). "Thus, insulin is needed for hyperglycemia to inhibit gastric glucagon secretion." (PMID 22969729, 2012). "Interestingly, acute infusion of glucagon resulted in sustained hyperglycemia as a consequence of stimulated gluconeogenesis and glycogenolysis in the liver, which, however, occurred only in human diabetic subjects with impaired β-cell function, but not in non-diabetic subjects." (PMID 23316165, 2012). "Moreover, high-selenium diets may stimulate the release of glucagon, promoting hyperglycemia, or may induce over-expression of glutathione peroxidase-1 (GPx-1) and other antioxidant selenoproteins resulting in insulin resistance and obesity." (PMID 20858268, 2010). "Therefore, to determine whether Men1 ablation prevents STZ-induced hyperglycemia through reducing the number of alpha cells, the average number and percentage of alpha cells in islets and circulating glucagon levels were determined." (PMID 21318185, 2010). "In addition to alterations of the insulin/glucagon axis, the direct effect of chronic hyperglycemia may affect the expression level of PGC-1α." (PMID 19142226, 2009). "In this study, hyperglucagonemia, despite hyperglycemia, was seen during DK/DKA and HHS using measurements of pancreas-specific glucagon with a sandwich ELISA." (PMID 41292690, 2026). "Stress hyperglycemia and inflammation have some common pathogenic mechanisms since both are related with cytokines’ release, such as tumor necrosis factor-α (TNF-α), which might promote gluconeogenesis by stimulating glucagon production, as well as inhibit post-receptor insulin signaling." (PMID 39860413, 2025). "In human islets from non-pregnant donors, serotonin, that is produced by β cells in response to hyperglycaemia, acts in a paracrine manner on α-cell serotonin 1 F receptors (5-HT1F) receptors to reduce glucagon secretion." (PMID 40691142, 2025). "The hyperglycemia observed in the IFG state and IGT state implicates a bi-hormonal effect in which glucagon raises the hepatic glucose output, and insulin diminishes the peripheral utilization of glucose." (PMID 38665134, 2024). "Glucoregulatory hormones modulate gastric emptying, contributing to postprandial hyperglycemia, and in a dose-dependent manner, fat and protein regulate GLP-1, GIP, and glucagon release after meals." (PMID 39519472, 2024). "Concomitant with increasing glucagon levels, serum insulin concentrations peaked approximately 2 h post-infusion in the CRI-HI group, an appropriate response to hyperglycemia that explains the normalization of glucose concentrations." (PMID 38814331, 2024). "Based on the fasting-induced hyperglycaemia observed in the mice transplanted with αTC1 WT cells, we evaluated the effect of CK2-mediated altered GCG expression on glucose tolerance and clearance." (PMID 38503901, 2024).
Hyperglycemia (continued). "Therefore, one could reason that during periods of general malnutrition and lack of building materials (protein), the enterocytes attempt to store glucose in the form of glucagon for a “better” metabolic time, while at the same time protecting the whole body from hyperglycemia." (PMID 39796104, 2024). "High glucagon serum increases the availability of glucose for brain energy under certain conditions, when the BBB permeability is increased due to hyperglycemia or neurodegenerative disease." (PMID 38977507, 2024). "Glucagon is stimulated by an elevation of FFA concentration and its anabolism in α-cells in the context of hyperglycemia, hyperlipidemia, and hypo-insulinemia, like glucose intolerance or diabetes." (PMID 38892240, 2024). "Studies in adult patients with T2D have shown a glucagon overproduction from α cells both while fasting and after a carbohydrate-rich meal, in response to an intravenous glucose load, and to arginine administration, thus suggesting an impaired α-cell regulation that could accentuate hyperglycemia." (PMID 37432389, 2023). "Although the exact mechanism by which β-cell-specific GLS2 regulates insulin and glucagon requires further study, our data indicate that GLS2 in pancreatic β-cells maintains glucose homeostasis under the condition of hyperglycaemia." (PMID 37147373, 2023). "Despite significant hyperglycaemia in Gls2 CKO mice after glucose loading, plasma glucagon, which is generated from pancreatic α-cells and functions as a key regulator of hepatic gluconeogenesis, was increased." (PMID 37147373, 2023). "Increased stress levels during the COVID-19 lockdown could also have led to hyperglycaemia through involvement in unhealthy behaviours, such as binge eating, reduced physical activities and the production of stress hormones, including cortisol, glucagon and the development of low-grade inflammation." (PMID 35162117, 2022). "The closure of KATP channels results in lower MP amplitude, and since glucagon exocytosis depends primarily on Ca2+ entry through P/Q-type voltage-gated calcium channels (VGCC) with high activation threshold, hyperglycemia reduces Ca2+ entry." (PMID 35448534, 2022). "GIP stimulates glucagon secretion especially at lower glucose concentrations, while GLP-1 suppresses glucagon secretion, in particular at hyperglycemia." (PMID 34680059, 2021). "It is possible that lesogaberan helped to correct hyperglycemia by acting on islet β-cell or α-cell GABAB-Rs and modulating insulin and/or glucagon release." (PMID 33418884, 2021). "While GLP-1 agonists stimulate insulin secretion and suppress glucagon production, SGLT-2-inhibitors improve hyperglycemia by enhanced glucosuria." (PMID 33808404, 2021). "Additionally, short-term hyperglycemia, such as during a 2-h hyperglycemic clamp, reduces plasma glucagon concentration, and suppresses endogenous glucose production in healthy individuals, and such effects may contribute to responses observed in the current study." (PMID 33178135, 2020). "In summary, hepatic glucagon resistance may result in a dysregulated lipid and amino acid/protein metabolism and possibly impaired autophagy, leading to excess accumulation of fat, increased oxidative stress, and hyperaminoacidemia, resulting in hyperglucagonemia and hyperglycemia." (PMID 33333850, 2020). "At hyperglycaemia GIP indeed stimulates insulin release, but in the presence of euglycaemia or hypoglycaemia GIP stimulates glucagon secretion." (PMID 26859145, 2016). "After 4 weeks of treatment, fasting hyperglycemia and hyperinsulinemia in HFD-fed mice were significantly improved, and fasting serum NEFA, 3-hydroxybutyrate, and plasma glucagon levels were significantly increased by ipragliflozin treatment." (PMID 26977813, 2016). "GLP-1 can be used against hyperglycemia and obesity in most T2DM diabetic patients by stimulating insulin secretion, inhibiting glucagon secretion, slowing gastric emptying, and promoting satiety." (PMID 27656657, 2016).